TGFB1 (transforming growth factor beta 1)
Diseases named in the same sentence as TGFB1 in open-access papers (continued):
Sharing a sentence is not in itself a finding about the gene and the disease.
nasal polyps (53 papers, 2011 to 2026). "Eosinophils infiltrating nasal polyps secrete TGFβ1, which leads to stromal fibrosis and basement membrane thickening." (PMID 39338148, 2024). "In the nasal polyp tissue, the expression of both TGFβ1 and TGFβ2 isoforms has been demonstrated." (PMID 39338148, 2024). "Similarly, TGFβ1 induces EMT in epithelial cells derived from nasal polyps or the inferior turbinate, with this effect being particularly pronounced in tissues with high levels of TGFβ1 and Smad3 compared to healthy tissue samples, consistent with our findings." (PMID 39338148, 2024). "Variations in goblet cell hyperplasia, collagen fibre density, and the expression of matrix metalloproteinase-9 (MMP-9) and transforming growth factor-beta 1 (TGF-β1) have also been noted between CRS cases with and without nasal polyps in the context of AR." (PMID 39131035, 2024).
acute myeloid leukemia (52 papers, 2011 to 2026). Acute myeloid leukemia (AML) is a group of neoplasms arising from precursor cells committed to the myeloid cell-line differentiation. "EVs from the sera of acute myeloid leukemia (AML) patients are enriched with membrane-bound TGFβ1, which significantly reduces the killing properties of NK-cells." (PMID 37371477, 2023). "Exogenous TGFβ1 induced accumulation of acute myeloid leukemia (AML) cells in a quiescent G0 state, which was further facilitated by the co-culture with BM-derived mesenchymal stem cells (MSCs)." (PMID 23826077, 2013).
adenoma (52 papers, 1999 to 2026). A neoplasm arising from the epithelium. "The TGFβ1 pathway was described to be decreased during pituitary tumorigenesis, especially in non-functioning adenoma, suggesting a tumor suppressor role for this gene." (PMID 26322309, 2015). "The comparative proteomic data show that Ras, ERK, JNK, p38-MAPK and Akt, TNF and TGFb1, and MAPK and NFkB are the key nodes in their pathway networks; and that ERK/MAPK signaling is the significant canonical pathway in adenomas." (PMID 20426862, 2010). "As there is considerable evidence suggesting that tumor cells may become not responsive to TGFβ1-dependent cell signaling, the levels and distribution of the two main receptors of TGFβ1 were analyzed in histological tissue sections of adenomas and adenocarcinomas." (PMID 22848630, 2012).
helminth infections (52 papers, 2007 to 2025). "IL-10 and TGFβ1 are T-regulatory cytokines that are important in regulating the immune response, and they play a major role in minimizing the pathology and boosting tissue repair during helminth infections." (PMID 32636589, 2020).
Hepatitis (51 papers, 2009 to 2026). Inflammation of the liver. "Under normal conditions, TGFβ1 acts as a tumor suppressor and pro‐apoptotic agent in adult hepatocytes, regulating liver mass, while genetic deletion of TGFB1 in mice on a BALB/c background led to the development of necroinflammatory IFN‐γ‐dependent hepatitis." (PMID 38970443, 2024). "This study primarily aimed to explore the effect of TGFB1 genetic polymorphism and its interaction with viral hepatitis on cognitive function in individuals with and without hepatitis." (PMID 38970443, 2024). "SNPs of TGFB1 and allelic frequency in the control and hepatitis groups." (PMID 38970443, 2024). "In addition, in vivo disruption of TGFβ1 expression by morpholinos attenuated fibrosis and iCCA progression, suggesting the importance of TGFβ signaling during hepatitis-induced iCCA." (PMID 31450767, 2019).
mesothelioma (51 papers, 2012 to 2025). A usually malignant and aggressive neoplasm of the mesothelium which is often associated with exposure to asbestos. "Similar therapeutic benefits were observed in multiple murine mesothelioma tumor models following administration of a soluble TGFβRII chimeric protein designed to neutralize TGFβ1 (and TGFβIII) and thereby abrogate its signaling in target cells." (PMID 27589814, 2016). "Therefore, we analyzed the mRNA expression levels of INHBA (activin-A subunit), TGFB1 and TGFB2 in mesothelioma cells." (PMID 29228689, 2017).
schizophrenia (51 papers, 2012 to 2025). A major psychotic disorder characterized by abnormalities in the perception or expression of reality. "Our results indicate that the TGFB1 +869T>C gene polymorphism is associated with schizophrenia, especially in females." (PMID 24065520, 2013). "TGFB1 gene is located within the chromosome 5q31–32, the region that has been most consistently associated with schizophrenia in genome-wide linkage analyses." (PMID 24065520, 2013). "We found that allele frequency and genotype distribution of the TGFB1 +869T>C polymorphism differed significantly between schizophrenia patients and healthy controls (p = 0.03 and 0.02 respectively)." (PMID 24065520, 2013). "Notably, network analysis placed Lox, Mmp9 and Tgfb1 at the core of the astroglial networks associated with AD (Fig. 3aii) and schizophrenia (Fig. 3bii)." (PMID 31477687, 2019). "Genetic variants in TGFB1 gene affect susceptibility to schizophrenia." (PMID 28117656, 2016). "Notably, we were unable to find a significant association between the remaining polymorphisms (IL2 −330T>G, IL6 −174G>C, IFNG +874T>A, TGFB1 +913G>C) and schizophrenia in our study." (PMID 24065520, 2013). "Polymorphisms of TGFB1, which encodes TGF-β, along with its additional overexpression were also associated with schizophrenia." (PMID 34501305, 2021). "There was a significant difference in the genotype distribution and allelic frequency of the TGFB1 +869T>C between patients with schizophrenia and healthy controls (p < 0.05)." (PMID 24065520, 2013). "Moreover, in the recent association study of 5q31–32 region, DNA pooling analysis revealed that TGFB1 gene is also a candidate gene for schizophrenia." (PMID 24065520, 2013). "On the other hand, we obtained strong evidence showing that two other schizophrenia-related genes, MMP9 and TGFB1, were not significantly altered according to the analysis of our PCR arrays." (PMID 29302405, 2017).
brain tumor (50 papers, 1994 to 2025). "Through comparative analysis of different brain tumor histologies, we detected that TGFB1 mRNA had the highest levels in astrocytoma, anaplastic astrocytoma, and GB compared to the other histologies." (PMID 38794149, 2024). "Among them, TGFβ1 and TGFβ2 are involved in brain tumor development and progression, particularly in high-grade GBM." (PMID 29132376, 2017). "Finally, we can indicate that TGFB1 is a marker of poor prognosis in brain tumors and correlates with the expression of HIFs, ectonucleotidases, and the ADORA3 gene involved in purinergic signaling in GB." (PMID 38794149, 2024). "Interestingly, these analyses did not only evidence increased levels of TGF-β1 transcripts (TGFB1) in GBM, they also showed the elevated presence of Vδ TCR chain transcripts (TRDC) in these brain tumors." (PMID 36741364, 2022). "A similar correlation in the expression level of the TGFβ1 isoform with respect to the grade of malignancy of the brain tumor was shown in our study, but the correlation was not statistically significant." (PMID 35454784, 2022).
Cerebral ischemia (50 papers, 2008 to 2025). Restriction of arterial blood supply to the brain associated with insufficient oxygenation to support the metabolic requirements of the tissue. "Rhodiola sp. can reduce TNF-α, transforming growth factor beta 1, and IL-6 levels in the BALF in a concentration-dependent manner and inhibit inflammatory injury caused by cerebral ischemia in rats, slowing the progression of brain edema." (PMID 35432571, 2022). "The contribution or involvement of TGFβ1, GDNF, NT-3, ERK or Akt in NCM-mediated brain protection against cerebral ischemia however, remained still unclear." (PMID 26745377, 2016). "The therapeutic potentials of NCM, TGFβ1, GDNF, NT-3 and DADS in the control of cerebral ischemia in human therefore have been suggested and require further investigation." (PMID 26745377, 2016).
renal carcinoma (50 papers, 2010 to 2025). A carcinoma arising from the epithelium of the renal parenchyma or the renal pelvis. "TGFB1 has enhanced the proliferation and metastatic potential of renal carcinoma by upregulating lymphoid enhancer-binding factor 1/integrin αMβ2." (PMID 35222525, 2022). "TGFB1 is a key cytokine produced by proximal tubular and renal cancer cells, and regulates various vital processes and contributes to tumor progression and aggression in ccRCC." (PMID 33371886, 2020). "By targeting both TNKS1 and CDK8, TCS9725 is expected to disrupt critical signaling pathways involved in renal cancer progression, including STAT1, β-Catenin, and TGFβ1-Smad signaling, which are known to drive cancer cell proliferation and metastasis." (PMID 40699862, 2025).
prostate tumor (48 papers, 2008 to 2026). "TGFβ1 stimulation induces prostate tumour cell scattering and increases the expression levels of Snail and N‐cadherin through the TRAF6‐mediated activation of Rac1/Pak1 pathway." (PMID 29193723, 2018). "Al‐Azayzih observed that stimulation with TGFβ1 induced prostate tumour cell scattering and increased expression of Snail and N‐cadherin through TRAF6‐mediated activation of Rac1/Pak1 pathway." (PMID 29193723, 2018). "Overrepresented genes from the WNT and transforming growth factor, beta 1 (TGFB1)/bone morphogenetic protein (BMP) transduction cascades were validated in the public gene expression database of prostate tumors." (PMID 24739220, 2014).
pancreatic adenocarcinoma (45 papers, 2002 to 2025). "Pancreatic adenocarcinoma tumors exhibit increased levels of mRNA expression for components of the Transforming growth factor-β pathway (TGFB1/2/3, TGFBR1/2/3) and Interferon Type I pathways (IFNAR1, STAT1, IRF9 and IFI27)." (PMID 39457004, 2024). "A recent report has shown that silencing Nrp1 diminished TGFβ signaling in pancreatic adenocarcinoma cells, but also inhibited TGFβ1-induced Smad2 phosphorylation in endothelial cells (HUVECs) and blocked endothelial to mesenchymal transition and fibrosis." (PMID 28938007, 2017). "This is consistent with the high levels of TGFβ1 observed in pancreatic adenocarcinoma and chronic pancreatitis." (PMID 12434297, 2002). "In TGF-induced pancreatic adenocarcinoma (PANC-1) cells, silencing of DUSP26 expression by siRNA markedly suppressed the effect of TGFβ1 on E-cadherin and mesenchymal genes in the cells." (PMID 37476896, 2023).
skin cancer (44 papers, 2007 to 2026). "In this context it has been previously reported that the loss of TGFβ1 expression resulted in hyperproliferation of skin and skin tumours of mice." (PMID 38256034, 2024). "TGFβ1 induces α11 expression in skin myofibroblasts during wound healing, and we observed higher levels of TGFβ1 in Itga11-/- skin tumors as compared to Itga11+/+ tumors." (PMID 36003785, 2022). "Although there are three distinct TGFβ family members, TGFβ1, β2, and β3 all of which have been detected in skin and skin tumors, nearly all mouse models have focused on TGFβ1." (PMID 23326666, 2012). "While these mice did not develop skin cancers, this model illustrates the critical nature of latent TGFβ1 activation for generating sufficient TGFβ1 in the microenvironment for normal tissue homeostasis." (PMID 23326666, 2012). "Levels of TGFβ1 and ILT3 were in fact very similar to those seen in the primary skin tumours." (PMID 17565341, 2007). "However, according to our data, the Itga11-/- skin tumor CAFs do not respond as efficiently to TGFβ1 induction as the control CAFs, as demonstrated by the downregulation of fibrillar collagen and TNC biosynthesis in the knockout tumors." (PMID 36003785, 2022). "Finally, although nearly all of these studies have been done in the chemical carcinogenesis model, for cutaneous cancer at least, it is not clear if alterations in TGFβ1 signaling would impact UV-induced skin cancer in the same way." (PMID 23326666, 2012).
dilated cardiomyopathy (43 papers, 2008 to 2025). Cardiomyopathy which is characterized by dilation and contractile dysfunction of the left and right ventricles. "Studies have shown that TGFβ1-Smads signalling pathway are markedly up-regulated at the site of injury after MI, in patients suffering from dilated cardiomyopathy, and all these conditions are characterised by excessive fibrosis in the heart." (PMID 26068068, 2015).
experimental autoimmune encephalomyelitis (43 papers, 2013 to 2026). An autoimmune demyelinating disease of the central nervous system that is produced experimentally in animals by the injection of homogenized brain or spinal cord in Freund's adjuvant. "Astrocyte targeted overexpression of TGFβ1 resulted in earlier and more severe experimental autoimmune encephalomyelitis, while systemic administration inhibited disease." (PMID 31829262, 2019). "Previous studies have reported that systemic administration of TGFβ1 attenuates experimental autoimmune encephalomyelitis (EAE) in mice, suggesting a protective role of TGFβ in EAE." (PMID 34675988, 2021).
lymph node metastasis (43 papers, 1994 to 2025). "While these findings are exploratory, their study revealed a genotypic correlation between lymph node metastasis and transforming growth factor beta 1 (TGFB1) rs1800460 of 0.29 (p < 0.05) and its recessive GCTG haplotype of -0.32 (p < 0.05)." (PMID 39593069, 2024). "High expression of TGFβ1 is correlated with a high incidence of lymph node metastasis." (PMID 22995475, 2012). "Conversely, in CAFs, NR2F1 expression was higher in T3 or tumors with lymph node metastasis, TGFB1 was higher in larger T categories or without lymph node metastasis, and there was little difference in SOX9 expression." (PMID 35740627, 2022). "CXCL14 and TGFβ1 were not correlated with lymph node metastasis, staging, or overall survival." (PMID 34167551, 2021). "ROC curves were generated for serum TGFβ1 to evaluate its ability to distinguish PDTC from benign pancreas disease, lymph node metastasis from non-lymph node metastasis and stages I and II from stages III and IV." (PMID 27464025, 2016).
colorectal tumors (42 papers, 1996 to 2025). "The expression of TGFβ1 in both tumor and plasma was found to be significantly higher in patients with metastatic colorectal cancer, and increasing colorectal tumor stage was correlated with higher TGFβ1 expression in tumor tissues." (PMID 21845215, 2011).
anemia (41 papers, 2011 to 2025). A reduction in the number of red blood cells, the amount of hemoglobin, and/or the volume of packed red blood cells. "On the other hand, it was shown that inhibiting TGFβ1 signaling could improve anemia in MDS patients." (PMID 37925591, 2023).
chronic pancreatitis (41 papers, 2002 to 2025). A chronic inflammatory process causing damage and fibrosis of the pancreatic parenchyma. "We found that TGFβ1 can cause downregulation in IA currrents, also similar to what we have previously observed in pancreatic nociceptors of rats with chronic pancreatitis." (PMID 22963239, 2012). "TGFβ1 is an important and complex modulator of sensory neuronal function in chronic inflammation, providing a link between fibrosis and nociception and is a potentially novel target for the treatment of persistent pain associated with chronic pancreatitis." (PMID 22963239, 2012). "TGFβ1 is a proinflammatory factor that stimulates the activation of PSCs during the development and progression of chronic pancreatitis towards early pancreatic neoplasia." (PMID 36835366, 2023). "Further TGFβ1 infusion into the naïve rat pancreas in vivo induces hyperalgesia and conversely, neutralization of TGFβ1 attenuates hyperalgesia only in rats with experimental chronic pancreatitis." (PMID 22963239, 2012). "Conversely, TGFβ1 antagonism can attenuate hypersensitivity and hyperalgesia in chronic pancreatitis, a painful inflammatory condition." (PMID 22963239, 2012). "Here we show that TGFβ1 can directly sensitize nociceptors, induce pancreatic hyperalgesia and contribute to the enhanced nocifensive response that accompanies chronic pancreatitis." (PMID 22963239, 2012). "We also studied the effects of TGFβ1 infusion on pain responses to noxious electrical stimulation in healthy rats as well as the effects of neutralization of TGFβ1 on evoked pain behaviors in a rat model of chronic pancreatitis." (PMID 22963239, 2012). "In order to understand the underlying basis for the changes observed in this study, we focused on the effects of TGFβ1 on Kv currents, which we have previously shown to be significantly downregulated in our model of chronic pancreatitis." (PMID 22963239, 2012). "We next assessed the effects of neutralization of TGFβ1 on pain behavior in a rat model of chronic pancreatitis using a neutralizing antibody which has been shown to be effective in antagonizing TGFβ1 effects lasting up to six weeks or more." (PMID 22963239, 2012). "The neuronal transcription factor Pou4f1 has been identified as a Smad3 target gene in bone marrow-derived macrophages stimulated by transforming growth factor-beta 1 (TGF-β1), implicating the TGF-β1/Smad3 axis in nociceptive signaling in chronic pancreatitis." (PMID 41163091, 2025).
glomerular diseases (41 papers, 2005 to 2025). "TGFβ1 signaling is associated with glomerulopathy where TGFβ1 could induce the production and aberrant deposition of different laminins (including laminin β1) on the glomerular basement membrane (GBM) as an initial signal for pro-fibrosis stages of lupus nephritis." (PMID 32265909, 2020). "Apparently, inhibition of HuR with KH-3 is able to further disrupt the positive TGFβ1/HuR feedback circuit in glomerular disease." (PMID 32478392, 2020). "Collectively, these observations elucidate an important link between cellular HuR activation and signaling of TGFβ1, NF-κB, and Nox4 in glomerular disease." (PMID 32478392, 2020). "TGFβ1 induces fibrosis during tissue repair process and contribute to the pathogenesis of a variety of glomerular diseases." (PMID 25279306, 2014). "Tgfβ1-expression is known to be associated with podocyte damage by the stimulation of extracellular matrix accumulation, while estrogen supplementation was shown to prevent Tgfβ1 mediated glomerulopathy." (PMID 22096576, 2011). "Increased TGFβ-1 was generally observed in human glomerulopathies related cases." (PMID 32908562, 2020).
leiomyoma (41 papers, 2007 to 2026). A well-circumscribed benign smooth muscle neoplasm characterized by the presence of spindle cells with cigar-shaped nuclei, interlacing fascicles, and a whorled pattern. "In leiomyomas, luteolin attenuates fibrosis and normalizes apoptotic and TGFB1/PI3K/PTEN signaling." (PMID 41821610, 2026). "Importantly, in human leiomyomas, most of these signaling pathways, such as upregulation of mTOR, TGFB1 and CTNNB1 pathway, deregulation of IGF-1 signaling in human uterine leiomyoma and inflammatory process involving TNF signaling have been reported." (PMID 33244099, 2020). "It has been demonstrated that TGFB1-stimulated expression of fibromodulin may contribute to the fibrotic properties of leiomyoma." (PMID 25478164, 2014). "In vitro studies documented that TGFβ-1 treatment and vitamin D3 have opposite effects on α-SMA, TGFβR2 and VDR expression on dermal fibroblast and leiomyoma cell cultures." (PMID 37606484, 2023).
muscular dystrophy (41 papers, 2010 to 2026). Muscular dystrophy (MD) refers to a group of more than 30 genetic diseases characterized by progressive weakness and degeneration of the skeletal muscles that control movement. "Inhibition of TGFβ1 has proven beneficial in mouse models of muscular dystrophy, but the global strategies of TGFβ1 inhibition produce significant detrimental side effects." (PMID 34575582, 2021).